UGT2B17 (UDP glucuronosyltransferase family 2 member B17)
Diseases named in the same sentence as UGT2B17 in open-access papers (continued):
Sharing a sentence is not in itself a finding about the gene and the disease.
kidney disorder (2 papers, 2010 to 2023). A disease involving the kidney. "Benefit - harm evaluations in therapeutic use of anabolic steroids should also consider this potential link between UGT2B17 gene deletion polymorphism and renal disorders." (PMID 20429943, 2010). "If the hypothesis is upheld, anabolic steroid users with a deletion mutation in the UGT2B17 gene may be exposed to an increased risk of developing renal disorders." (PMID 20429943, 2010). "Hence, we postulate that UGT2B17 gene homogeneous polymorphism (del/del) increases the chance of developing renal disorders with prolonged use of AAS due to increase in BMI and direct toxic effect of steroids on kidneys." (PMID 20429943, 2010). "An animal study involving chronic administration of AASs to mice or rats with different UGT2B17 genotypes, accompanied with routine examination of renal function will help in scrutinizing the relationship between development of renal disorders and deletion polymorphism in the gene." (PMID 20429943, 2010). "We hypothesize that UGT2B17 deficient individuals are more vulnerable to developing renal disorders with prolonged use of AAS owing to increases in body mass index and possible direct toxic effects of steroids on the kidneys." (PMID 20429943, 2010). "However, if the hypothesis is correct, these athletes expose themselves to an increased risk in developing renal disorders as a consequence of their UGT2B17 gene deletion polymorphism." (PMID 20429943, 2010). "We hypothesize that with chronic and/or excessive use of AAS, individuals with a deletion polymorphism in the UGT2B17 gene (del/del) carry an increased risk of developing renal disorders owing to an increase in body mass index and possible direct toxic effects of steroids on the kidneys." (PMID 20429943, 2010). "Therefore, in this paper we hypothesise that the observed renal disorders among AAS users is connected to the genetic profiles of these users and functional polymorphic deletion of the UGT2B17 gene significantly increases the chance of developing kidney complications." (PMID 20429943, 2010).
metabolic disease (1 paper, 2025). A congenital disorder (due to inherited enzyme abnormality) or acquired (due to failure of a metabolically important organ) disorder resulting from an abnormal metabolic process. "In addition, recent genome-wide association studies identified UGT2B17 as an effector gene for circulating levels of total cholesterol, apolipoprotein B, low density lipoprotein-cholesterol and triglycerides as well as associations between androgen levels and metabolic diseases." (PMID 40264209, 2025).
UGT2B17 also shares sentences with these, for which no sentence is quoted: endometrial cancer (2 papers); head and neck carcinoma (2); adenocarcinoma (1); ankylosing spondylitis (1); Arthritis (1); benign prostatic hyperplasia (1); cervical cancer (1); dependence (1); diabetes (1); glioblastoma (1); heart failure (1); Hypertension (1); larynx (1); metastatic disease (1); nicotine dependence (1); oral squamous cell carcinoma (1); prostate adenocarcinoma (1); squamous cell carcinoma of esophagus (1).